GFAP (glial fibrillary acidic protein)
Diseases named in the same sentence as GFAP in open-access papers (continued):
Sharing a sentence is not in itself a finding about the gene and the disease.
multiple sclerosis (continued). "Moreover, recent data based on the EAE-model indicate increased GFAP-levels being a promising marker of the chronic disease stage in generally and of the secondary progressive disease phase in particular in patients with multiple sclerosis." (PMID 20386697, 2010). "This study investigates the significance of glial fibrillary acidic protein (GFAP) and ubiquitin C-terminal hydrolase L1 (UCHL-1) in cerebrospinal fluid (CSF) of patients with multiple sclerosis (MS) and peripheral neuropathy (PN)." (PMID 39565457, 2025). "Recently, glial fibrillary acidic protein (GFAP) has garnered attention as a potentially valuable biomarker for various neurological disorders, including multiple sclerosis, frontotemporal dementia, AD, and Parkinson's disease." (PMID 39534430, 2024). "Only in primary progressive MS (PPMS), serum GFAP correlated strongly with expanded disability status scale (EDSS) (Spearman rho = 0.6, p = 0.002) and with age-related multiple sclerosis severity score (ARMSS) (spearman rho = 0.4, p = 0.04)." (PMID 30287870, 2018). "Ischemic infarction, acute disseminated encephalomyelitis (ADEM), multiple sclerosis (MS), Marchiafava–Bignami disease (MBD), osmotic demyelinating syndrome (ODS), and autoimmune glial fibrillary acidic protein (GFAP) astrocytopathy were excluded by image findings." (PMID 40114853, 2025). "We stained for GFAP+ astrocytes, CCL2-producing (RFP+) cells, and Iba-1+ cells, which include microglia, macrophages, and mature monocytes, as these cells have been found to produce CCL2 in other neuroinflammatory diseases, including multiple sclerosis." (PMID 38206985, 2024). "In other clinical populations, such as AD patients, exercise interventions have reduced plasma levels of p-tau and t-tau, but not NfL, whereas in patients with multiple sclerosis, exercise interventions have reduced plasma levels of NfL and GFAP." (PMID 38488949, 2024). "Non-obese diabetic mice (model for secondary progressive multiple sclerosis) pro-inflammatory active astrocytes (GFAP+).Pro-inflammatory reactive astrocytes." (PMID 38891053, 2024). "Non-obese diabetic mice (model for secondary progressive multiple sclerosis) pro-inflammatory active astrocytes (GFAP+)." (PMID 38891053, 2024). "The presence of astroglia activation in AD [23▪▪,24▪▪,25▪▪], as well as in non-AD disorders, such as multiple sclerosis and frontotemporal lobar degeneration, support the use of plasma glial fibrillary acidic protein (GFAP) as a blood biomarker [26,27▪]." (PMID 36607770, 2023). "Interestingly, the astrocyte marker protein GFAP has been reported to be found in blood from patients suffering from a number of neurodegenerative diseases including Alzheimer's, ALS, and multiple sclerosis." (PMID 28663721, 2017). "However, RFs can also be observed in the brains of other central nervous system diseases, such as multiple sclerosis and ciliary astrocytoma or when non-mutant GFAP is highly overexpressed." (PMID 39596168, 2024). "Furthermore, the evidence that specific CNS proteins are detectable in blood, as shown by this study, may open up avenues of investigation in CNS injury for neurodegenerative disorders, multiple sclerosis or HIV, where GFAP and NfL are regularly investigated." (PMID 33737684, 2021). "Furthermore, these biomarker levels were positively correlated with EDSS scores in patients with NMOSD (r = 0.303, p = .002 for YKL‐40; r = 0310, p = .001 for sCD14; r = 0.250, p = .011 for sCD163), but not in patients with multiple sclerosis or glial fibrillary acidic protein astrocytopathy." (PMID 36306394, 2022). "Moreover, in a cohort study on multiple sclerosis (MS), serum GFAP levels failed to predict disease activity and progression, whereas CSF GFAP levels were significant predictors despite a correlation existing between CSF and serum GFAP levels and other glial/neuroinflammation markers." (PMID 40346659, 2025).
multiple sclerosis (continued). "In another study, GFAP concentration of 0.8 (0.6–1.1) (median, IQR) μg/mg of total protein in non-lesional white matter in 12 patients with multiple sclerosis was reported." (PMID 35765081, 2022). "In agreement with our results, CLU mRNA levels were reported to be elevated in glial fibrillary acidic protein-positive astrocytes in white matter lesions over NAWM, but not in grey matter of multiple sclerosis patients." (PMID 32272486, 2020). "Increased cerebrospinal fluid (CSF) eosinophils, neutrophils, glial fibrillary acidic protein (GFAP), or neurofilament light chain and the absence of CSF-restricted oligoclonal IgG bands also argue in favor of NMOSD over multiple sclerosis." (PMID 32961928, 2020). "Established and convenient blood markers for astroglial integrity like glial fibrillary acidic protein (GFAP) have not yet been investigated in ME/CFS and may not reflect neuroglial dysfunction in the absence of cellular disintegration (as seen in multiple sclerosis or traumatic brain injury)." (PMID 35614970, 2022).
Parkinson disease (93 papers, 2009 to 2026). A progressive degenerative disorder of the central nervous system characterized by loss of dopamine producing neurons in the substantia nigra and the presence of Lewy bodies in the substantia nigra and locus coeruleus. "Reactive gliosis associated with a drop in GFAP phosphorylation has been reported, for example, in the neurodegenerative condition in Parkinson’s disease." (PMID 32982688, 2020). "We conducted an analysis using a confocal microscope to examine the expression of three neuronal markers that are generally downregulated in Parkinson’s disease patients, glial fibrillary acidic protein (GFAP), tyrosine hydroxylase (TH), and microtubule-associated protein 2 (MAP2)." (PMID 40227236, 2025). "Additionally, diminished levels of PPARα and NURR1—proteins essential for neuronal survival—along with elevated expression of IBA1 and GFAP, markers of microglial activation and astrocytic gliosis, respectively, are associated with the pathogenesis of Parkinson’s disease." (PMID 40422188, 2025). "For example, a recombinant adenovirus expressing GDNF under the GFAP promoter was injected into the striatum of a Parkinson’s disease rat model, demonstrating neuroprotective effects." (PMID 40456763, 2025). "In Parkinson’s disease mouse models, the oral administration of the 4b analogue improved dyskinesia, reduced the expression of glial fibrillary acidic protein (GFAP; a marker of neuroinflammation) and increased a number of tyrosine hydroxylase-positive cells." (PMID 38611422, 2024). "The expression levels of GPNMB are elevated in the substantia nigra of patients with Parkinson's disease (PD) and the GFAP-positive astrocytes." (PMID 39263169, 2024). "Astrogliosis, measured as the volume of GFAP+ signal, was similarly observed in the striatum of the different models of parkinsonism." (PMID 38610019, 2024). "Our observed impact of age on GFAP levels is in line with previous observations in people living with Parkinson’s disease where GFAP was shown to correlate with both age and MMSE." (PMID 39271655, 2024). "Cortical tau retention correlated with plasma levels of GFAP (p = 0.001) and pTau181 (p = 0.036).ConclusionsSubcortical 18F-Florzolotau uptake assist the diagnosis of 4R tauopathy parkinsonism." (PMID 39973504, 2024). "Particularly, radotinib protects against α-synuclein preformed fibrils (PFF)-induced neuronal cell death and restores α-synuclein PFF-induced activation of Iba-1-positive microglia and GFAP-positive astrocytes in Parkinson’s disease models." (PMID 37569615, 2023). "Astrogliosis (increased GFAP labeling) and microgliosis (increased Iba-1 labeling) were significantly enhanced in the Parkinson’s disease group." (PMID 33479244, 2021). "A large number of activated microglia revealed by enlarged somata and astrocytes containing GFAP were identified in SNpc of the monkey with Parkinsonism." (PMID 34691601, 2021). "The literature reveals that TRX exhibits a mitigating effect in Parkinson’s 6-OHDA rat model not only via antioxidation activity but also through inhibition of astroglial GFAP expression partially by modulating the function of PI3K/ERβsignalling pathway." (PMID 32797057, 2020). "In agreement with our mouse experiment, we found an increase in oligomeric α-syn in GFAP+ astrocytic processes of Parkinson’s disease patients in cortex (~ 2 folds), striatum (~ 2 folds), and cerebellum (~ 2 folds)." (PMID 32641150, 2020). "In contrast to the overexpression of GFAP seen in animals treated with ADSCs, it was shown that ADSC-EVs markedly decreased the gene expression of GFAP, restored astrocytic injury, and improved motor performance in their Parkinson’s disease model." (PMID 32194404, 2020). "AßP-42, tau protein, α-synuclein, asialoganglioside GM1, GFAP, rab-5, ATP-synthase, MBP, and their antibodies have been linked with neurodegeneration and diseases such as AD, Parkinson's disease (PD), and multiple sclerosis (MS)." (PMID 30034864, 2018).
Parkinson disease (continued). "Lastly, DAG also accumulated in GFAP-positive astrocytes in mTHY-1/α-synuclein overexpressing mouse model of Parkinson’s disease." (PMID 29123083, 2017). "On the contrary, in a rat Parkinson’s model, the neuroprotective effect induced by 3 mg kg−1 rosiglitazone (i.p.)is concomitant with an increase in GFAP expression in the hippocampus." (PMID 25036594, 2014). "The three highest individual GFAP values were found in a case of Parkinson’s disease (0.85 μg/l), in a patient with subarachnoid hemorrhage (0.71 μg/l), and in a case of bacterial meningitis (0.67 μg/l)." (PMID 23626774, 2013). "Furthermore, GFAP has been investigated in the context of Parkinson’s disease as a biomarker of disease progression." (PMID 39064479, 2024). "The rate of GFAP‐positive cells in Parkinson's disease (PD) rat models (n = 3, ±SD, %)." (PMID 37721421, 2024). "Numerous in vivo and in vitro studies have shown that regulating GFAP in astrocytes is not only beneficial for understanding the physiology of healthy brains but also serves as a biomarker for neurological diseases like Alzheimer’s and Parkinson’s disease." (PMID 38146544, 2023). "The uptake of EVMetS by C6 cells induced a strong increase in GFAP and TNF-α mRNA expression, suggesting that EVMetS promote astroglial pro-inflammatory responses, an event that has been extensively associated with the progression of Parkinson’s disease." (PMID 38136165, 2023). "rTMS with different frequencies has been shown to regulate the expression of GFAP (a cytoskeletal marker of astrocytic reactivity) and the density of GFAP-positive astrocytes in various in vivo brain injury or disease model, such as cortical stab injury, Parkinson’s disease, etc." (PMID 37283739, 2023). "Moreover, recently a case of GFAP-astroglial autoimmunity presented with reversible parkinsonism, suggesting the close relationship between these entities." (PMID 35364741, 2022). "In agreement with previous studies, our study showed that the toxin MPTP induces phenotypes associated with Parkinson’s disease in mice such as decreased levels of dopamine and GSH; increased levels of MDA, iNOS, and TNF-α; and increased numbers of GFAP positive astrocytes." (PMID 33796021, 2021). "Interestingly, in Alzheimer’s and Parkinson’s diseases, increased GFAP expression seems to correlate with the severity of astroglial activation." (PMID 32964397, 2021). "In addition to the hippocampus of Alzheimer (n = 6) and control brains (n = 6), GFAP+1 positive astrocytes were found in the striatum (caudate/putamen) of control and Parkinson brains." (PMID 19888461, 2009). "However, GFAP levels have been correlated with levels of monoamine oxidase B (MAO-B) in post-mortem Parkinson’s brains, suggesting that MAO-B could be used as a potential marker of astrocytic reactivity." (PMID 39404391, 2024). "In addition to TH, Iba1 and GFAP immunohistochemistry, a range of different proteins involved in processes that may be impaired in Parkinson-GBA1 (such as autophagy, lysosomal functioning and endoplasmic reticulum stress) were analysed by western blotting." (PMID 28969384, 2017). "Interestingly, chronic treadmill running also normalises levels of striatal glial fibrillary acidic protein (GFAP) in mouse models of Parkinson’s disease suggesting that reductions in markers of pathology may also be possible in humans with this condition." (PMID 26064521, 2015). "Therefore, GFAP astrocytosis may also contribute to Parkinson’s disease in patients." (PMID 39911384, 2025). "GFAP and NfL levels were analyzed in plasma and CSF samples of 47 MSA patients as well as 24 Parkinson’s disease (PD) and 25 healthy controls (HC) as reference cohorts." (PMID 39254698, 2024). "Mucuna pruriens administration significantly decreased glial fibrillary acidic protein (GFAP), iNOS, intercellular cell adhesion molecule (ICAM), and TNF-α inflammatory parameters in MPTP-induced Parkinson's disease (PD) animals." (PMID 36589679, 2022).
Parkinson disease (continued). "Glial fibrillary acidic protein (GFAP) is the principal intermediate filament in mature astrocytes and has been investigated as a marker of astrocytic activation in AD, Parkinson's disease and amyotrophic lateral sclerosis." (PMID 35478426, 2022). "In a mouse model of Parkinson's disease, researchers successfully induced the transdifferentiation of midbrain astrocytes into dopaminergic neurons by using an AAV vector expressing shPtbp1, driven by the GFAP promoter." (PMID 40702752, 2025). "These GFAP.HMOX18.5–19m mice are affected by parkinsonism unlike younger GFAP.HMOX10–12m mice who have schizophrenia-like features." (PMID 29751692, 2018). "In agreement with this hypothesis, lipid droplets were observed in glial fibrillary acidic protein (GFAP)-positive astroglial cells in the penumbra of transient brain ischemia in rats, and a recent study showed an accumulation of neutral lipids in a cellular model of Parkinson’s disease." (PMID 35453664, 2022).
brain tumors (85 papers, 1980 to 2026). "Like the unmodified forms, the citrullinated peptide fragment of GFAP and vimentin therefore appeared to be associated with pediatric brain tumors with a lower degree of aggressiveness, according to the WHO classification." (PMID 37761239, 2023). "As this combination, GFAP-positive astrocytes demonstrated an activating form around the tumor and allowed us to depict the association of reactive astrocytes with brain tumors more accurately." (PMID 35474103, 2022). "Serum neuronal biomarkers, such as neuron-specific enolase (NSE), S100β, and glial fibrillary acidic protein (GFAP), have been reported to be upregulated in patients with brain tumors caused by brain injuries." (PMID 28969023, 2017). "From a practical diagnostic viewpoint, GFAP is a reliable immunohistochemical marker for staining surgically resected brain neoplasms to ascertain whether they have a significant component of cells differentiating along the astrocytic pathway." (PMID 35573835, 2022). "However, GFAP in the blood cannot be used as a specific diagnostic marker for a brain tumor because it exhibits a so-called "sensitivity gap" due to the heterogeneous/low expression of GFAP on some tumors, which leads to undetectable amounts of GFAP released into the bloodstream." (PMID 34210107, 2021). "Finally, markers suggested in this review such as PlGF and GFAP have to be evaluated for its diagnostic potential for difficult-to-diagnose patients (e.g., in the differential diagnosis of metastasis versus primary brain tumor)." (PMID 25720744, 2015). "This study is the first demonstration that activated astrocytes with strong GFAP signals were the primary cells responsible for the APOE production at the brain tumor edge." (PMID 40745073, 2026). "This case offers a rare presentation of GFAP-positive lung adenocarcinoma metastasis to the brain and validates the combined histological, immunohistochemical, and molecular approach to brain tumor diagnosis." (PMID 42211592, 2026). "first described chordoid glioma (CG) as a brain tumor typically located near the third ventricle, characterized histologically by glial fibrillary acidic protein (GFAP)-positive tumor cells surrounded by a myxoid matrix." (PMID 41333225, 2025). "The astrocytes are hijacked by brain tumor cells to reactive with proliferation, hypertrophy, and enhanced expression of GFAP." (PMID 38951862, 2024). "Among the 12 pediatric brain tumor cases included in our study, the CTCs were sorted out and validated with positive GFAP immunofluorescence staining in 7 diffuse glioma and 2 ependymoma cases." (PMID 37046450, 2023). "Brain tumours dissected from these mice were found to have less penetrance of GFAP+ cells into the tumour mass, and in the overall brain, possibly indicating a reduced migration/invasion ability of the astrocytes via miR‐146a‐5p inhibition." (PMID 37759347, 2023). "(K) Quantification of the colocalization coefficient of CD31 and GFAP staining in the brain tumor sections of mice injected with MGG8-GSC/shNT and MGG8-GSC/shFMOD cells." (PMID 35642785, 2022). "(J) Confocal microscopy analysis showing CD31 and GFAP expression in brain tumor sections of mice injected with MGG8-GSC/shNT or MGG8-GSC/shFMOD cells." (PMID 35642785, 2022). "(L) The number of blood vessels with co-staining of CD31 and GFAP was quantified in brain tumor sections of mice injected with MGG8-GSC/shNT and MGG8-GSC/shFMOD cells and plotted." (PMID 35642785, 2022). "Glial fibrillary acidic protein is presently the most prevalent marker for the identification of circulating tumor cells, and expression is frequently maintained in brain tumors, despite its heterogeneity." (PMID 34210107, 2021). "First, a transgenic mouse model expressing E2F1 in GFAP‐expressing cells (thus including neural precursors) developed brain tumors, including MBs." (PMID 32920979, 2021).